EGFR (epidermal growth factor receptor)
Diseases named in the same sentence as EGFR in open-access papers (continued):
Sharing a sentence is not in itself a finding about the gene and the disease.
lung cancer (continued). "This BIM deletion polymorphism occurs in 12–16% of lung cancer patients with EGFR mutations." (PMID 33363040, 2020). "Notably, epidermal growth factor receptor (EGFR) mutation-positive lung cancer patients with high PAK1 expression showed higher mortality rates than those with low PAK1 expression (91.3% vs. 62.5%, p = 0.02)." (PMID 33261184, 2020). "However, many patients with suspected advanced nonsmall cell lung cancer are unable to undergo biopsy thus forgoing potential treatment with highly effective tyrosine kinase inhibitors (TKIs) in patients with sensitizing EGFR mutations." (PMID 31991049, 2020). "Here, for the first time, we report that vitamin D activity may be restricted to a specific molecular subtype of lung cancer, adenocarcinomas harboring mutations in the EGFR gene." (PMID 32183160, 2020). "To determine whether the system could detect circulating EGFR mutations in liquid fluids, we collected cell-cultured supernatants, which mimicked body fluids, of H1975 lung cancer cells." (PMID 32093010, 2020). "This is the first prospective study showing that ctDNA genotyping provides a feasible diagnostic approach for frail lung cancer patients who are unable to undergo biopsy, which subsequently leads to EGFR‐targeted therapy, and improved outcomes in this subgroup of patients." (PMID 31991049, 2020). "There are several models that might explain the discordance of EGFR mutation between primary lung cancer and BM." (PMID 32483122, 2020). "Moreover, studies conducted on erlotinib-treated lung cancer patients with EGFR mutations have shown that a specific polymorphism (181946C > T) in EGFR gene is associated with long-term progression-free and overall survival." (PMID 32937815, 2020). "e., KRAS and EGFR mutations), other genes may harbor mutations that could be relevant for lung cancer." (PMID 32082488, 2020). "Of note, mTOR upregulation is also considered a cause of resistance to EGFR-inhibitors in lung cancer patients, implying that they might also display metabolic vulnerability." (PMID 32943635, 2020). "TTF-1, a routine IHC index of lung cancer, may be a biomarker to predict the unknown EGFR mutation status." (PMID 32742498, 2020). "However, among those who recurred, EGFR-mutated lung cancer had increased rates of metastatic recurrence compared to EGFR-wildtype disease (97% vs 68%, p = 0.007)." (PMID 32523650, 2020). "The prevalence of EGFR mutation in unselected lung cancer in Indonesia is about 44%." (PMID 33425389, 2020). "Thus, this phase II study aimed to evaluate the safety and efficacy of osimertinib in elderly patients with EGFR-mutated lung cancer involving the T790M mutation." (PMID 32517152, 2020). "EGFR mutation positivity was associated with longer OS, suggesting that the prognosis of EGFR mutation‐related lung cancer could be improved by EGFR‐targeted therapy, which may also apply to incidences of resected NSCLC." (PMID 32022477, 2020). "The influence of common lung cancer mutations (i.e., EGFR, ALK, etc.)or programmed cell death-ligand 1 (PD-L1) in the PFDN expression could be elucidated in this further study." (PMID 32344577, 2020). "The underling molecular mechanism of Ezrin activation in lung cancer involves Ezrin modifications (such as phosphorylation and S-nitrosylation), epidermal growth factor receptor (EGFR), and EGFR-mediated signaling pathways in non-small cell lung cancer (NSCLC) cells." (PMID 33240887, 2020). "Lung cancer development is associated with mutations in the EGFR gene." (PMID 33207677, 2020). "First, we examined only three GIST cell lines and two EGFR-mutated lung cancer cell lines." (PMID 31857719, 2020). "Furthermore, mutation status (EGFR/ALK) in lung cancer and receptor status (ER/PR/HER2) in breast cancer also exhibit diversity in their response to radiotherapy." (PMID 32733787, 2020).
lung cancer (continued). "The combination of afatinib and bevacizumab in chemo-naïve EGFR-mutated advanced lung cancer was investigated in a previous study (Okayama Lung Cancer Study Group Trial 1404), but that study was focused on the feasibility of this combination, not its efficacy." (PMID 33113888, 2020). "In the present study, we hypothesized that radiomics from contrast-enhanced T1-weighted images of BMs could be applied to predict EGFR mutation status in primary lung cancers." (PMID 32483122, 2020). "These novel findings may be crucial in considering therapeutic strategies that cure or dramatically improve the prognosis of EGFR-mutated lung cancer." (PMID 32929081, 2020). "BMs from lung cancer with epidermal growth factor receptor (EGFR) L858R mutations occurred more often in the caudate, cerebellum, and temporal lobe than those with an exon 19 deletion of EGFR." (PMID 32984041, 2020). "In addition, 18F-FDG PET derived radiomic features have been shown to anticipate the treatment response to TKIs in EGFR-mutated lung cancer." (PMID 33370365, 2020). "EGFR‐TKIs upregulate BIM expression to induce apoptosis of lung cancer cells with EGFR mutations." (PMID 32508032, 2020). "Moreover, the comparative IPA analysis predicted the MNK1/2 causal network highly and differentially activated under the L858R mutation status, which have been targeted by several chemical drug inhibitors for EGFR mutation-positive lung cancers." (PMID 32983988, 2020). "Our results indicate that optimal inhibition of the tolerant signal via IGF-1R combined with osimertinib may dramatically improve the outcome of AXL-low-expressing EGFR-mutated lung cancer." (PMID 32929081, 2020). "EGFR-mutated lung cancers are especially relevant, as EGFR activation can activate RAS signaling, and patients with EGFR mutations may have a concomitant gain-of-function KRAS mutation." (PMID 33335263, 2020). "Mutations in the epidermal growth factor receptor (EGFR) are drivers of a subset of lung cancers." (PMID 32776462, 2020). "Specifically, EGFR mutations may impact treatment with gefitinib, which is a tyrosine kinase inhibitor used to treat lung cancers." (PMID 32059456, 2020). "ITGB8 was also found to be amplified in the EGFR-mutated group of lung cancer." (PMID 32175330, 2020). "Thus, the most frequent application of LB in lung cancer is the determination of mutations in EGFR to identify genomic mechanisms of resistance to targeted therapy and detected PD-L1 expression for immunotherapy." (PMID 32629823, 2020). "In this regard, lung cancer investigations revealed that smoking could increase the EGFR and its downstream elements, such as KRAS and BRAF mutations." (PMID 33127962, 2020). "Indeed, discordant rates of EGFR mutation status between primary lung cancer and BM in previous studies range from 0 to 66.7%69–75." (PMID 32483122, 2020). "Recently, there has been a revolution in our understanding of lung cancer biology with the detection of driver mutations such as epidermal growth factor receptor (EGFR) mutation as well as the exploration of the role of immune system dysfunction in cancer progression." (PMID 33194687, 2020). "Here, we retrospectively screened next‐generation sequencing (NGS) data from 24 468 lung cancer patients, and a total of 85 unique EGFR e20ins variants were identified in 547 cases (2.24%), with p.A767_V769dup (25.1%) and p.S768_D770dup (17.6%) being the most prevalent ones." (PMID 32412152, 2020). "Thus, stratification of EGFR mutation-related phenotypes by antioxidant gene polymorphism status can be an effective approach in terms of improving the prognosis of lung cancer patients." (PMID 32937815, 2020). "Three alternatives are currently available for the use of first- or second-generation epidermal growth factor receptor tyrosine kinase inhibitors (EGFR-TKIs) to treat EGFR-mutated lung cancer, such as single agents or combinatorial treatment with an anti-VEGF antibody or chemotherapy." (PMID 33008313, 2020).
lung cancer (continued). "TAS-116 may be a novel promising drug to overcome tyrosine kinase inhibitor-resistance in both GIST and EGFR-mutated lung cancer." (PMID 31857719, 2020). "Importantly, nuclear ERβ1 expression in lung cancer tissues was associated with tumor-suppressing effects, whereas cytoplasmic ERβ1 promoted EGFR TKI resistance to some extent." (PMID 33585221, 2020). "We anticipate analogous results may be obtained in EGFR-mutant lung cancers that lose RB1 since these variants are likely to up regulate EZH2." (PMID 32292420, 2020). "Similarly, some studies have shown that activation of STAT3/Bcl-2/caspase 3 signaling can promote apoptosis of NSCLC cells, and acquired resistance of EGFR-mutated lung cancer to TKI treatment is related to the anti-apoptosis effect of the PARP pathway." (PMID 32778129, 2020). "Consequently, it is incumbent on physicians to determine the mutation status of EGFR and other therapeutically targetable mutations of lung cancer patients to guide precision therapy and prognostic assessment of patient health." (PMID 32722209, 2020). "Moreover, a recently published paper showed that induction of Mig-6 under hypoxic conditions was critical for dormancy in primary cultured lung cancer cells, with activating EGFR mutations and dormant cells being more resistant to EGFR-TKIs." (PMID 32552717, 2020). "Another implication of our data is that vitamin D supplementation may be of critical importance, particularly among lung cancer patients with EGFR mutations." (PMID 32183160, 2020). "In conclusion, we demonstrated here that T1-enhanced radiomics using RF classification may predict EGFR mutation status in lung cancer BMs with a high degree of accuracy." (PMID 32483122, 2020). "The survival time of lung cancer patients bearing common EGFR mutations (Exon 19 deletion or L858R point mutation) has been markedly improved with the FDA approval of first-generation EGFR tyrosine kinase inhibitors (TKIs), gefitinib and erlotinib." (PMID 32575680, 2020). "As proven by several large-scale clinical trials, epidermal growth factor receptor (EGFR)-tyrosine kinase inhibitors (TKI) are highly effective in lung cancer patients harboring EGFR activating mutations, mainly, deletions in exon 19 (Del19) and a L858R mutation in exon 219–13." (PMID 32034239, 2020). "In the study by Gou and Wu which demonstrated the frequencies of driver mutations in non‐small cell lung cancer in China, the mutation rates of EGFR were 48.4% (675/1795), 4.3% (9/208), and 28.2% (570/2021) in lung adenocarcinoma, squamous cell cancer (SCC) and NSCLC, respectively." (PMID 31794146, 2020). "Here, we explored whether radiomic features of contrast-enhanced T1-weighted images (T1WIs) of BMs predict EGFR mutation status in primary lung cancer cases." (PMID 32483122, 2020). "Of the lung cancer patients, four had proven targetable EGFR mutations in their tumor tissues." (PMID 32093010, 2020). "Additionally, the population was only of Asian origin, and the first-line therapy in China for EGFR-mutated lung cancer differed from the United States and other places, which limit the applicability and generalization of the data." (PMID 32411590, 2020). "In conclusion, EGFR is a relevant therapeutic target for mRCC in combination with anti-angiogenic treatment but only in the presence of a relevant mutation, different to those described in lung cancer." (PMID 31938054, 2020).
lung cancer (continued). "ALK gene rearrangement occurs in a small portion of patients with non-small-cell lung cancer (NSCLC), but it accounts for about 30%–40% of lung adenocarcinoma in young individuals, and is present in many non-smokers and patients with epidermal growth factor receptor (EGFR)-mutated lung cancer." (PMID 32283823, 2020). "To test this hypothesis, we compared the performance of EFIRM and ddPCR in detecting the EGFR L858R mutation in vitro using various lengths of gDNA fragments (140 to 750 bp) from the human H1975 lung cancer cell line harboring the L858R mutation." (PMID 32722209, 2020). "MAP2K1 mutation has been identified among subsets of smoking-associated lung carcinomas (mutually exclusive from EGFR, BRAF, KRAS, and NRAS mutations), lung adenocarcinoma in situ and early invasive disease, and KRAS/NRAS/BRAF/PIK3CA wild-type (“quadruple-wild-type”) colorectal carcinomas." (PMID 32483240, 2020). "Moreover, the CA9 SNP rs2071676 AG + GG was correlated to a lower tumor stage and lower risk for developing lymph node metastasis in lung carcinoma accompanied by wide type of EGFR." (PMID 32365566, 2020). "We used CR for the detection of EGFR mutation from sputum with lung carcinoma cell lines." (PMID 32033355, 2020). "The development of tyrosine kinase inhibitors (TKIs), targeting the epidermal growth factor receptor (EGFR), and the sequential detection of activating EGFR mutations as a molecular marker for tumor sensitivity to these drugs, has positively impacted lung cancer management." (PMID 31534543, 2019). "Then we conducted a second literature research to curate case reports of familial lung cancers who studied both germline cancer predisposing genes and their somatic EGFR mutation status; and explored the possible links between cancer predisposing genes and EGFR mutation." (PMID 31703574, 2019). "Many human lung cancers have a mutation in the gene that makes the protein EGFR." (PMID 31741433, 2019). "Several preclinical studies have proved that osimertinib was active in specific lung cancer cell lines with EGFRex20ins mutations, while the clinical activity of the 3rd generation EGFR TKIs in EGFRex20ins tumors remains unknown." (PMID 31208370, 2019). "In an analysis of infiltrated immune cells in subtypes of lung cancer, researchers found that LUADs with K-ras or EGFR mutations were more densely infiltrated by cells of myeloid lineage, whereas small cell lung cancers (SCLCs) were mostly infiltrated by T cells." (PMID 32039025, 2019). "Although the Brazilian Ministry of Health considers that anti-EGFR TKI is a therapeutic option in cases of advanced lung cancer with the presence of EGFR mutation, the reimbursement offered by the Ministry of Health is insufficient for targeted therapy to be used." (PMID 32159636, 2019). "Some studies have shown that lung cancer patients with EGFR mutation who are treated with targeted TKIs, such as erlotinib, afatinib, or gefitinib, show longer progression-free survival and higher objective radiographic response rates than patients treated with standard first-line chemotherapy." (PMID 30956990, 2019). "Many patients with adenocarcinoma, a major subtype of lung cancer, harbor mutations in the epidermal growth factor receptor (EGFR) in their cancer tissues and initially show a good response to molecular targeted drugs such as gefitinib, which inhibits the EGFR tyrosine kinase." (PMID 30532069, 2019). "Individuals with non‐small cell lung cancer (NSCLC) positive for activating mutations of the epidermal growth factor receptor (EGFR) gene are sensitive to first‐ and second‐generation EGFR–tyrosine kinase inhibitors (TKIs) such as gefitinib, erlotinib, and afatinib." (PMID 31419057, 2019). "Therefore, our results are useful to guide the selection of lung cancer, even EGFR-mutated adenocarcinoma patients with PD-L1 expression, for further immunotherapy." (PMID 31561631, 2019).
lung cancer (continued). "Hence, accurate molecular pathology testing especially EGFR mutations detection has been an expert consensus in lung cancer clinical practice." (PMID 31555581, 2019). "Furthermore, gefitinib-responsive lung cancers were demonstrated to express EGFR mutation with more effective to the drug than EGFR wild-type." (PMID 35582586, 2019). "Moreover, BTK inhibition re-sensitized lung cancer cells to either EGFR-targeted or SOC chemo-therapies disregarding EGFR/KRAS mutational status." (PMID 31200752, 2019). "Since it is well known that EGFR mutations usually lead to the abnormal expression of itself and promotes cellular proliferation in lung cancer, we investigated the roles of PRDX4 in the proliferation of two human LUAD cell lines, A549 cells (EGFR wild-type) and PC-9 cells (EGFR mutant)." (PMID 31588184, 2019). "Our results demonstrated that this kit could also be used reliably to detect EGFR mutations in plasma ctDNA isolated from lung cancer patients." (PMID 31185703, 2019). "In patients with EGFR-mut lung cancer, TMB has been shown to be associated with a poor response to tyrosine kinase inhibitors, and a meta-analysis of clinical trial data reported that patients with EGRF-mut tumors demonstrate a poor therapeutic response to immunotherapies." (PMID 31762941, 2019). "Furthermore, high levels of IL-8 have been associated with resistance to lung cancer therapies such as EGFR inhibitors, conventional chemotherapy, and anti-PD-1 immunotherapy." (PMID 32039025, 2019). "Extracting the DNA from fixation liquid of lung cancer biopsy may be a kind of feasible way to detect EGFR mutation." (PMID 31315782, 2019). "Notably, EGFR or KRAS mutated lung cancer accounts for a significant subgroup of NSCLC, especially in adenocarcinoma." (PMID 31088477, 2019). "Somatic EGFR mutations in these lung cancers are tentatively deletions or insertions." (PMID 31703574, 2019). "Germline EGFR mutations are very rare, less than 1/7500 (0.01%) in the general population; the proportion is higher in sporadic lung cancers, namely 1/555 (0.18%) of lung ADCs from TCGA (mostly White) and 14/12,833 (0.11%) of Chinese lung cancers." (PMID 31703574, 2019). "In addition, the expression of PTEN, MYC, EGFR, and Vimentin, potential indicators associated with lung cancer patients survival period, was also detected in A549 lung cancer cells." (PMID 31508368, 2019). "Thus, it will be interesting to investigate the potential role of CPGs in the pathogenesis of somatic EGFR mutation in lung cancer." (PMID 31703574, 2019). "A recent review reported additional potential biomarkers that are associated with brain metastasis from lung cancer, including the epidermal growth factor receptor, KRAS, anaplastic lymphoma kinase rearrangements, single-nucleotide polymorphisms, miroRNAs, and others." (PMID 31226155, 2019). "Moreover, several NGS-based studies have reported an incidence of EGFR compound mutations of 3.0 to 16% in EGFR-mutated lung cancers." (PMID 30808329, 2019). "Lung cancer is the most common cause of cancer-related mortality worldwide despite diagnostic improvements and the development of targeted therapies, notably including epidermal growth factor receptor (EGFR) tyrosine kinase inhibitors (TKIs)." (PMID 31262325, 2019). "Their findings that EGFR mutations are more common in non‐COPD lung patients might indicate that lung cancer development depends on activating EGFR mutations in non‐COPD patients." (PMID 30706659, 2019). "A large number of genetic alterations (> 200) have been identified in human NSCLC; for example, the v-Ki-ras2 Kirsten rat sarcoma virus oncogene (KRAS) and epidermal growth factor receptor (EGFR) are the most commonly mutated oncogenes that drive the pathogenesis of lung cancer." (PMID 31554189, 2019).